CCER1 (coiled-coil glutamate rich protein 1)
Description:
Regulator of histone epigenetic modifications and chromatin compaction into the sperm head, required for histone-to-protamine (HTP) transition. HTP is a key event in which somatic histones are first replaced by testis-specific histone variants, then transition proteins (TNPs) are incorporated into the spermatid nucleus, and finally protamines (PRMs) replace the TNPs to promote chromatin condensation.
Synonyms: C12orf12; MGC26598
Tractability: No criterion of Open Targets' tractability assessment is met for any kind of drug.
Gene: Protein-coding gene on chromosome 12 (90,905,622 to 90,955,176, reverse strand). Ensembl gene ENSG00000197651.
Subcellular location: Nucleus
Gene Ontology:
Molecular function: protein binding
Biological process: sperm DNA condensation; spermatogenesis
Cellular component: nucleus
Genetic constraint (gnomAD): Loss-of-function variants: 1 observed, 1.64 expected, observed/expected ratio (o/e) 0.61, 90% interval 0.2 to 1.81. That is too few expected variants to judge how well the gene tolerates losing a copy. Missense variants: 515 observed, 462.43 expected, observed/expected ratio (o/e) 1.11, 90% interval 1.03 to 1.2. Synonymous variants: 223 observed, 190.74 expected, observed/expected ratio (o/e) 1.17, 90% interval 1.05 to 1.31.
Homologues: Orthologues: chimpanzee CCER1 (95% identical), macaque CCER1 (86% identical), pig CCER1 (70% identical), rabbit CCER1 (65% identical), rat Ccer1 (62% identical), mouse Ccer1 (61% identical), dog CCER1 (61% identical), guinea pig CCER1 (58% identical).
Diseases named in the same sentence as CCER1 in open-access papers:
CCER1 is named in the same sentence as 4 diseases in open-access papers, as found by Europe PMC text mining. Sharing a sentence is not in itself a finding about the gene and the disease. The quoted sentences say what the papers report.
Azoospermia (1 paper, 2023). Absence of any measurable level of sperm,whereby spermatozoa cannot be observed even after centrifugation of the semen pellet. "Here the authors reveal that phase‐separated nuclear CCER1 condensates are required for male fertility by mediating chromatin condensation and histone epigenetic modification, while loss‐of‐function variants of human CCER1 are pathogenic in patients with nonobstructive azoospermia (NOA)." (PMID 38081819, 2023). "Notably, we identified loss-of-function (LoF) variants of human CCER1 (hCCER1) in five patients with nonobstructive azoospermia (NOA) that were absent in 2713 fertile controls." (PMID 38081819, 2023).
Infertility (1 paper, 2023). "In contrast, CCER1 deficiency results in defective sperm chromatin compaction and infertility in mice." (PMID 38081819, 2023). "In sum, our data suggest that Ccer1 is a gene that causes infertility that mediates nuclear chromatin condensation via LLPS in germ cells." (PMID 38081819, 2023). "Tolerance to CCER1 mutations may contribute to differences in the type and degree of infertility in humans and mice." (PMID 38081819, 2023). "Idiopathic infertility is often associated with mutations in genes, we screened for potential mutations in the gene coding regions in a cohort of 620 patients with NOA and found CCER1 mutations can be pathogenic to human spermatogenesis." (PMID 38081819, 2023).
male infertility (1 paper, 2023). The inability of the male to effect fertilization of an ovum after a specified period of unprotected intercourse. "Collectively, the results support that nuclear CCER1 forms a phase-separated condensate in the mouse testes, and mutations identified in both human patients and mice affect the phase separation of CCER1 and lead to the loss of CCER1 function and pathogenesis, specifically male infertility." (PMID 38081819, 2023). "Importantly, we also show the mutations in human CCER1 gene link spermatogenesis and male infertility in the population, which is a major issue in human health." (PMID 38081819, 2023). "Thus, the loss of CCER1 affects the development of spermatids during spermiogenesis (the process of spermatid development) and causes male infertility in mice." (PMID 38081819, 2023).
CCER1 also shares sentences with these, for which no sentence is quoted: cancer (1 paper).